COL3A1 (collagen type III alpha 1 chain)
Diseases named in the same sentence as COL3A1 in open-access papers (continued):
Sharing a sentence is not in itself a finding about the gene and the disease.
tumor (continued). "Subsequently, profiling the TIME of PDAC revealed that Col3a1 KD within tumor cells slightly enhanced the infiltration of immune cells, particularly CD8+ T cells." (PMID 39316363, 2024). "The CosMx data also revealed that C1QC+ macrophages, CCL5+ T cells, and IGHG1+ plasma cells were more abundant near one tumour subclone while COL3A1+ fibroblasts were more abundant near the other." (PMID 38570491, 2024). "For example, collagens, such as COL1A1, COL1A2, COL3A1, COL5A2, COL6A1, COL6A2, and COL6A3 are thought to mediate tumor progression and are associated with a poor prognosis in BCa." (PMID 37277784, 2023). "Among all LR communication partners that were screened in BRCA BoM datasets, only COL3A1 had higher expression in c9 fibroblasts derived from tumor samples compared to c9 fibroblasts derived from other samples." (PMID 38187400, 2023). "To confirm that IER3 was expressed in CAFs, we used antibodies against IER3 and collagen type III α 1 chain (COL3A1, a marker of fibroblast) to stain a subset of tumor specimens from cohort 3 (19 samples from 11 patients)." (PMID 37424047, 2023). "Collagen such as COL1A1/COL1A2/COL3A1 can change the resistance of tumor cells by interacting with the ITGB1 integrin, as reported for other cancers." (PMID 36460803, 2023). "Seven hub genes (AXL, EFEMP2, VIM, EHD2, FSTL3, ALOX5, HSPB8) were downregulated in tumor samples, while COL3A1 was upregulated in tumor samples in the TCGA dataset." (PMID 37291533, 2023). "In additions, clusters 4, 7 and 10 expressed a variety of collagen proteins including COL1A1, COL1A2, COL3A1, COL6A1 and COL6A3, which have been previously linked to abilities of proliferation, invasion, metastasis and drug resistance of tumor cells." (PMID 37644609, 2023). "Among all LR communication partners that were screened in BRCA BoM datasets, only COL3A1 had higher expression in osteoblasts derived from tumor samples compared to osteoblasts derived from other samples." (PMID 38187400, 2023). "GUCA2A were low expressed in both normal and tumor tissues and COL3A1 was positively expressed in both normal and tumor tissues, but significantly stronger in certain tumor tissues." (PMID 37816854, 2023). "Col1a2 and Col3a1 are more expressed when Vascular smooth muscle cells contact Tumor III cells (VSMC+Tumor III)." (PMID 37815040, 2023). "The fibrillar collagens COL2A1, COL11A1, and COL11A2 show higher expression in the solid tumour region and other fibrillar collagens, COL1A2 and COL3A1, show higher abundance in the brain/tumour interface region." (PMID 38001067, 2023). "GUCA2A were significantly downregulated in tumor tissues compared with normal tissues (− 0.41-fold, p-value: 0.0007) and COL3A1 were significantly upregulated in tumor tissues comparison with healthy tissues (7.18-fold, p-value: 0.0001)." (PMID 37816854, 2023). "Identification of collagen genes COL5A1, COL5A2, and COL3A1 as top key regulators points to a tumor microenvironment with significant fibrosis and desmoplastic change." (PMID 36637997, 2023). "Significant factors for OS were T stage (p < 0.01), clinical tumor stage (p = 0.048 < 0.05) and COL3A1 expression levels (p < 0.01)." (PMID 36039012, 2023). "We found that the expression levels of EFEMP2, EHD2, FSTL3 and ALOX5 were decreased in tumor tissues, whereas COL3A1 was significantly increased in tumor samples." (PMID 37291533, 2023). "ITGA2 was highly expressed in the spots adjacent to the tumor stroma expressing COL3A1 of post-treatment tumors." (PMID 36505794, 2022). "After that, we mapped the expression level of the pair co-expressed between post-treatment tumors and tumor stroma (COL3A1; ECM ligand and ITGA2; ECM receptor) on the tissue section." (PMID 36505794, 2022). "Tentative identification of the discriminative molecular features showed that collagen fragments (COL1A1, COL1A2, and COL3A1) play a fundamental role in tumor development." (PMID 35956764, 2022).
tumor (continued). "Risk factors, like STC1, COL5A2, COL3A1, and BGN, were significantly correlated with poor OS, while BMPR2 and PGLYRP1 were only found to be protective factors in 2 of 33 tumor types." (PMID 36479101, 2022). "COL3A1 upregulation was positively related to a worse prognosis, advanced tumor stage, local recurence and invasion, tumor-infiltrating immune cells (TIICs) recruitment, ECM-receptor interaction, and regulation of actin cytoskeleton and adhesion pathways." (PMID 36278695, 2022). "From the analysis of the most relevant m/z features for the classification, as calculated by forward feature extraction, we can conclude that COL1A1, COL1A2, and COL3A1 play a central role in tumor progression." (PMID 35956764, 2022). "Reportedly, COL3A1 was substantially overexpressed in the liver invasion front of the colorectal liver metastases compared with the tumor center and the normal tissues, suggesting a potential role of this gene in metastasis." (PMID 33562096, 2021). "COL1A2, COL3A1, COL5A1 encode the collagen family, whose members are the main components of the tumor-stromal environment and play an important role in behavior of cancer cells." (PMID 34795689, 2021). "We previously showed that collagen (COL1A1 and COL3A1) mRNAs are increased in tumor tissues from CRC patients compared with normal tissue adjacent to the tumor." (PMID 34966673, 2021). "No study has shown the relationship between COL3A1 and IFN‐γ, but we assume COL3A1 down‐regulated type II IFN response to promote angiogenesis in tumour." (PMID 32757451, 2020). "What's more, Beeswam plots for new tumour event (P = 0.006) and recurrent (P = 0.003) showed the clinical relationship of COL3A1." (PMID 32757451, 2020). "For instance, PUC-GBC2 showed elevated expression of COL3A1, which encodes an extracellular matrix (ECM) protein (collagen α‐1(III)) associated with tumor progression and has been reported as a marker of poor prognosis." (PMID 32293552, 2020). "COL1A1 and COL3A1 mRNA expression was significantly increased in tumor tissue compared to adjacent non-tumor tissues in colons from CRC patients (P < 0.0001 and P < 0.03)." (PMID 32171282, 2020). "Since it has been reported that, in various invasive cancers, the overexpression of COL3A1 promotes tumor progression and confers poor prognosis, we therefore investigated the possible effects of COL3A1 in modifying iCCA cells behaviour." (PMID 31687002, 2019). "The IHC results showed that COL3A1 protein staining was mainly localized in the cytoplasm of tumor cells, but at varying intensity in the 95 RNA sequenced samples." (PMID 31533654, 2019). "Focusing attention on the ECM proteins found overexpressed in the iCCA with respect to NCT, COL3A1 appeared to play a primary role in promoting different tumor pathological features." (PMID 31687002, 2019). "We believe that our findings contribute to the understanding of the molecular basis underlying the iCCA-induced desmoplastic reaction and suggests COL3A1 as a promising molecular target in hampering tumor expansion and metastatic dissemination." (PMID 31687002, 2019). "The IHC results showed that the COL3A1 protein was mainly localized to the cytoplasm of tumor cells and the vast majority of samples were COL3A1-positive (n = 87, 92%)." (PMID 31533654, 2019). "In our previous work, MTUS1 frameshift insertion was associated with differences in gene expression and overall survival, and COL3A1 gene expression were shown to correlate with tumor aggressiveness." (PMID 31533654, 2019). "We focused on the collagen type III alpha 1 chain (COL3A1) stromal overexpression, demonstrating its involvement in iCCA cells migration and in the tumor-associated collagen re-organization." (PMID 31687002, 2019). "In this context, our findings on the involvement of type III collagen in tumor-induced collagen alignment, as well as in promoting iCCA cells migration, urge to further investigate the COL3A1 as potential molecular target." (PMID 31687002, 2019).
tumor (continued). "Alternatively, the sensitive signature showed only a single gene with significantly increased expression in tumors (COL3A1), implying that these genes are less likely to be detected in large tumor panels compared to our selections based on resistance." (PMID 29599910, 2018). "Along with previously reported genes such as WNT, we identify CAF-derived targets such as ARAF and COL3A1 upon which the tumor compartment depends for spheroid development." (PMID 29245949, 2017). "COL3A1, which is an essential component of the extracellular matrix, has been identified in cancer-associated fibroblasts within the TNBC tumor microenvironment, suggesting that it may facilitate the metastasis process through specific signaling pathways." (PMID 40867231, 2025). "Notably, COL3A1 expression was significantly higher in T4 compared to all other T stages, indicating a stronger correlation between COL3A1 expression and tumor size in advanced stages." (PMID 41465316, 2025). "Although ECM components (including specific collagens such as Col1a1/2, Col3a1) have shown upregulated expression in some human malignancies and tumor microenvironments, in our rodent model these ECM changes likely represent adaptive responses to thermal stress rather than pre-neoplastic events." (PMID 41301502, 2025). "Enteric glial cells had fewer potential crosstalk genes, with top regulatory factors ANXA1, TIMP1, and HLA-A, and target genes such as COL1A1 and COL3A1, which may support tumor structure and growth." (PMID 40145096, 2025). "Notably, several genes involved in cell cycle regulation (CCND2, CDKN2A/C), tumor microenvironment (COL3A1, COL1A1), and growth factor signaling (FGF18, ERBB2) showed significant upregulation with fold changes ranging from 1.5 to 2.0." (PMID 41419500, 2025). "Furthermore, the COL3A1 mutant tumours exhibited increased infiltration of pro-inflammatory M1 macrophages and decreased infiltration of immune-suppressive M2 macrophages." (PMID 39530091, 2024). "Interestingly, the extracellular matrix protein-encoding genes such as FN1, TIMP1, COL3A1, COL4A1, and COL2A1 were discovered in spatial cluster 8, regarded as tumor stroma tissues." (PMID 39257581, 2024). "Moreover, upregulation of COL3A1 in disseminated tumor cells has been shown to shape the collagenous ECM architecture to induce and sustain dormancy of these cells." (PMID 37498672, 2023). "Moreover, a recent pan-cancer analysis, showed that COL3A1 is expressed in diverse tumor types and its expression is correlated not only with prognosis but with the immune microenvironment." (PMID 37907993, 2023). "Tumor-associated macrophages (TAMs) were identified by CD68, CD14, CD163 and HLA-DRA and cancer-associated fibroblasts (CAFs) were characterized by COL1A1, COL3A1, MMP2, and SPARC." (PMID 37007745, 2023). "The CAFs from non-demarcated boundary tumors stimulate matrigel invasion and tumorigenicity in a mouse tumor transplant model, in sharp contrast to CAFs from tumors with demarcated boundaries that have particularly high expression of COL3A1 and COL6A6 in gene expression microarrays." (PMID 37046676, 2023). "Even though the risk model and COL3A1 could be used to predict HNSCC patients' prognoses, the latter exhibited a better ability to predict HNSCC patients' tumor immune responses." (PMID 36039012, 2023). "Recent research has shown that mutations in single genes, such as POLE, NLRP3, COL3A1, and PTPRT could predict tumor TMB and immunotherapeutic response." (PMID 35884556, 2022). "Furthermore, significant higher expression of COL1A1 in dLN (vs BME p=0.0075, vs dLU p=0.013) and COL3A1 in BME (vs dLU p=0.007) indicates that the reciprocal production of ECM proteins by tumor cells is also affected by the ECM of the metastatic organ." (PMID 36741736, 2022).
tumor (continued). "There are, however, significant differences between PTMmut and overall mutations, with e.g., hornerin (HRNR, a paralog of FLG) being a top-10 PTMmut gene in 14/31 tumor types and versican (VCAN), collagen III (COL3A1) and XIV (COL14A1) all mutated in 9/31 tumor types." (PMID 33802493, 2021). "Studies indicated that COL3A1 is highly correlated with tumor progression and metastasis." (PMID 34229299, 2021). "Circulating bone formation (P1NP) and bone resorption (CTX) markers were not different between genotypes at 5 and 15 weeks and mRNA expression of the major collagens Col1a1, Col1a2 and Col3a1 appeared comparable in tumor-bearing bones at 5 weeks and in primary OS cells." (PMID 32686768, 2020). "But the expression of COL3A1 is similar in HCC samples compared with non-tumor liver tissues." (PMID 32746865, 2020). "The previously identified genes, MTUS1 and COL3A1, wherein carriers of MTUS1 frameshift insertion associated with a significant difference in gene expression and OS, and COL3A1 gene expression correlated with tumor aggressiveness, were also included in the selection." (PMID 31533654, 2019). "Eight of the nine tumor samples with strong COL3A1 intensity were of HGSC histotype." (PMID 31533654, 2019). "COL3A1 is part of the collagen family which may affect the tumor microenvironment to promote tumor progression by regulating the extracellular matrix via collagen degradation and re-deposition." (PMID 31533654, 2019). "This study demonstrated that let-7d may suppress RCC growth, metastasis and tumor macrophage infiltration at least partially through targeting COL3A1 and CCL7." (PMID 25193015, 2014). "Additionally, collagen proteins (COL1A1, COL1A2, COL3A1, COL11A1) were linked to tumor progression and metastasis, while chaperonin-containing TCP1 (CCT) complex proteins and microtubule-associated proteins (TUBA1C, TUBB) were implicated in cytoskeletal organization and chemotherapy resistance." (PMID 40867231, 2025). "C7 was enriched in tumors with high expression of COL3A1, which may promote tumor metastasis." (PMID 38010945, 2024). "Interestingly, COL3A1 was detected in almost all tumor samples only." (PMID 31687002, 2019). "For instance, COL3A1 plays a role in ECM stiffness and tumor invasion in both squamous and adenocarcinoma types, and PLAU and SPP1 have been implicated in promoting tumor cell migration and metastasis via interactions with integrins and the PI3K/AKT pathway." (PMID 41465316, 2025). "All PDGCAs expressed markers of tumor epithelial and stem cells (EPCAM, CDH1, KRT18, CA9, CD24, CD133), stromal and extracellular matrix components (COL3A1, COL5A1, DCN, PDGFRA, and PDGFRB), and mesenchymal stem cells (CD73, CD105, CD90)." (PMID 40723172, 2025). "Top hits include changes in transcriptional regulation (ZNF385B, SNORA65), tumour microenvironment (COL1A2, COL3A1), and metastatic processes (UCHL1, SUCNR1, THY1)." (PMID 40890143, 2025). "COL6A3 and COL3A1 are involved in extracellular matrix (ECM) remodeling, which is crucial for tumor progression." (PMID 40427760, 2025). "COL3A1 contributes to tumor infiltration and poor prognosis, whereas NPY plays a key role in tumor growth and progression." (PMID 39473365, 2025). "For example, in COL1A1, COL1A2, COL3A1 and COL5A1 HYP peptides were enriched in the tumor nodule boundaries, a pattern that was lost in P4HA2-depleted tumors." (PMID 40671813, 2025). "Knockdown and functional analysis of COL3A1 and COL4A1 in ESCA cells were performed to assess their tumor-promoting roles." (PMID 40087784, 2025). "In contrast, COL3A1 and FSTL1 were significantly overexpressed in SKCM-P, pointing to a potential role in early-stage tumor development and offering targets for early detection and intervention." (PMID 40943183, 2025).
tumor (continued). "Despite these differences, we believe the genes identified in our study—COL3A1, PLAU, and SPP1—have common roles in ECM remodeling, cell adhesion, and tumor cell migration, processes that are shared across cancer types." (PMID 41465316, 2025). "Functional assays demonstrated that knocking down COL3A1 and COL4A1 led to decreased cell proliferation, colony formation, and migration, indicating their critical roles in tumor progression." (PMID 40087784, 2025). "There was tumor-specific basal heterogeneity, but there was a trend towards an increase in the wound signature mRNAs especially in the Meso PCTS; all but COL3A1 genes were increased, but only FGF5 reached significance." (PMID 38744944, 2024). "In NED tumor tissues, which had far more variability in protein species detection, the top three most abundant species were also COL1A2, COL1A1, and COL3A1, respectively." (PMID 39347566, 2024). "In particular, CTHRC1+GREM1+ myCAF expressed high levels of collagens, including type-1 (COL1A1, COL1A6), type-3 (COL3A1), type-5 (COL5A2), and type-6 (COL6A1), which contribute to tumor cell migration and proliferation through collagen/integrin interactions." (PMID 39075108, 2024). "In contrast, eight genes (COL1A1, COL5A1, COL1A2, COL3A1, WNT2, C1QTNF3, ADAMTS2, GXYLT2) exhibited elevated expression in tumor compared to normal tissue." (PMID 39062832, 2024). "The TCGA and GETx datasets indicated that COL1A1, COL3A1, COL5A2, COL8A1, COL10A1, and COL12A1 genes were expressed much higher in tumor tissues than in the normal ones." (PMID 36900272, 2023). "We found that VIM-CD44, COL1A1-CD44, B2M-CD3D, and the interaction between the ligand COL1A1/COL1A2/COL3A1 and the ITGB1 receptor showed significant benefits in the tumor microenvironment of both patients." (PMID 36460803, 2023). "Although collagen has been demonstrated to affect T cells in tumor microenvironment, the role of COL1A1 and COL3A1 in promoting the migration and activity of immune cells has yet to be explored." (PMID 37415178, 2023). "The high purity of the fibroblast and tumor cell populations was confirmed by selective expression of cell type-specific genes including CDH1, EPCAM, and KRT8 for tumor cells and VIM, DCN, THY1, and COL3A1 for fibroblasts." (PMID 36868311, 2023). "Not only were many collagen genes overexpressed in tumor progression between T1 and T2 stages, but also the mRNA expression of these collagen genes, such as COL1A1, COL1A2, COL3A1, COL5A1, COL5A2, COL6A2, and COL6A3, was highly positively correlated." (PMID 36596829, 2023). "CAFs in endometrial carcinoma, identified by classic fibroblast markers ATCA2, COL1A1, COL3A1, and THY1, are divided into four subsets with distinct characteristic and exclusive expression patterns that perform unique functions in the tumor ecosystem." (PMID 37046676, 2023). "In the second step, we investigated the upregulated gene (COL3A1) and downregulated gene (GUCA2A) in the tumor and normal samples expression profile in CRC patients using RNA-Seq data and real-time PCR validation." (PMID 37816854, 2023). "Cluster 8 ECs (COL1A1, COL1A2, COL3A1, PDGFRB, and ACTA2) showed an endothelium-mesenchymal transformation phenotype, contributing to tumor progression and metastasis." (PMID 37533434, 2023). "The genes COL3A1, ISLR, and IFITM1 are specific for vascular cells and show up-regulation in the tumor and down-regulation in the periphery." (PMID 35327982, 2022). "COL3A1, a type III collagen, has been shown recently to play an important role in regulating tumor dormancy and reactivation." (PMID 36216799, 2022). "Col1a1, Col1a2, Col2a1, Col3a1, and Col5a2, which were commonly found in normal ECM of mouse, pig, and human breast tissues, were also identified in tumor ECM in addition to Col4a2, Col5a1, Col6a1, Col6a2, Col6a3, and Col7a1." (PMID 36547361, 2022).